TRPM1 (transient receptor potential cation channel subfamily M member 1)
Diseases named in the same sentence as TRPM1 in open-access papers (continued):
Sharing a sentence is not in itself a finding about the gene and the disease.
melanoma (continued). "Furthermore, AUY922 also suppressed the growth of A375 and Mel1617 cells, which are human melanoma cells expressing TRPM1." (PMID 34301262, 2021). "Indeed, the founding member of the TRPM (melastatin) subfamily, TRPM1, was discovered by comparing benign nevi and malignant melanoma." (PMID 32887395, 2020). "Consequently, MITF has been shown to suppress melanoma metastasis through its transcriptional activation of miR-211 via the TRPM1 promoter." (PMID 33003444, 2020). "The final 83 pathogenic/likely pathogenic (P/LP) germline variants (66 unique) in 71/264 (26.8%) melanoma patients were detected in 42/217 targeted genes and included five copy number variants (CNV; two in CHEK2 and SLC45A2, respectively, and one in TRPM1)." (PMID 33050356, 2020). "Down-regulation of TRPM1 predicts the poor prognosis of patients with melanoma." (PMID 31519770, 2019). "Actinomycin D suppressed the upregulation of TRPM1 mRNA, which is transcriptionally activated upon treatment of melanoma cells with BRAF inhibitor 37 but did not affect HIF1A mRNA, confirming that the dose of actinomycin used was sufficient to block transcription completely." (PMID 31727958, 2019). "For example, although TRPM1 (transient receptor potential cation channel subfamily M member 1) is expressed in melanocytes mediating melanin production in melanoma, TRPA1 promotes tumour progression and invasiveness and is linked to a more aggressive disease phenotype." (PMID 31003534, 2019). "TRPM1 (also called melastatin) involvement in melanoma is undeniable." (PMID 29875336, 2018). "Furthermore, in primary melanoma patients high TRPM1 levels correlate with longer disease free survival (DFS)." (PMID 28445987, 2017). "In melanoma cells, TRPM1 is prevalent in highly dynamic intracellular vesicular structures.TRPM3 exists as multiple splice variants four of which (mTRPM3α1, mTRPM3α2, hTRPM3a and hTRPM31325) have been characterised and found to differ significantly in their biophysical properties." (PMID 29055033, 2017). "Nevertheless, TRPM1 expression in mice melanoma cells is reduced during metastasis." (PMID 25710007, 2015). "Taking in consideration the loss of expression of TRPM1 channel during the progression of melanomas toward more invasive forms it could be hypothesized that TRPM1 presence and/or activation inhibits migration." (PMID 24204345, 2013). "Downregulation of TRPM1/melastatin mRNA in primary malignant melanoma is a prognostic marker for metastasis; however, the pathobiologic role of TRPM3 in endometrial carcinoma remains largely unknown." (PMID 24321270, 2013). "Further, because TRPM1 was shown to exhibit tumor suppressor properties, decreased expression may serve as a biomarker for the development of a highly differentiated, aggressive form of melanoma since TRPM1 concentrations consistently decrease with the progression of the disease." (PMID 37445615, 2023). "S100A1 interaction with TRPM-1 could therefore be an important component in melanoma progression." (PMID 33256110, 2020). "In addition, high levels of miR-211 in melanoma-derived Exo were shown to indicate a reduced sensitivity to BRAF inhibitors, the mechanism of which involves the over-expression of MITF, a regulator of the TRPM1 gene, resulting in the prolonged survival of melanoma cells." (PMID 29755693, 2018). "Isoforms of TRPM1 may present in melanocytes, melanoma, brain, and retina." (PMID 29055033, 2017). "The gene encoding miR-211 is located within the sixth intron of the TRPM1 gene, which encodes multiple polypeptide isoforms including melastatin-1, a transient receptor potential (TRP) protein family member thought to be a potential suppressor of melanoma metastasis." (PMID 21072171, 2010). "In alpaca melanocytes and melanoma cells, SYT4 overexpression regulates calcium influx through TRPM1 and promotes dendrite elongation." (PMID 40354322, 2025). "However, the particular function of TRPM1 in melanomas and skin melanocytes remains unclear." (PMID 41118703, 2025).
melanoma (continued). "This review highlights the physiological expression of key TRP subfamilies (TRPM1, TRPM7, TRPM8, TRPV1, TRPV4, and TRPM2) in melanocytes and discusses their dysregulation in melanoma cells." (PMID 40869148, 2025). "In the context of melanoma, several TRP channel subtypes, including TRPM1, TRPM7, TRPV1, and TRPV4, have been shown to be differentially expressed and functionally active in tumor cells." (PMID 40869148, 2025). "Altered expression patterns and functional changes in TRPM1, TRPM7, TRPM8, TRPV1, and TRPV4 have notably been found to modulate cell survival, apoptosis, proliferation, and migration in melanoma models." (PMID 40869148, 2025). "As previously discussed, other members of the TRPM subfamily (TRPM1, TRPM5, TRPM7, and TRPM8) appear to have essential roles in melanoma." (PMID 37445615, 2023). "On the other hand, several metastatic lines—including IGR37—regained significant expression of TRPM1 and showed reduced expression of KCNMA1, KCNN4, and TRPM2, compared to the primary melanoma lines (third row)." (PMID 34445066, 2021). "The most cancer‐specific dysregulated miRNA in melanoma is miR‐211‐5p, which is indeed transcribed by MITF together with its host gene, melastatin (TRPM1), in human melanocytes." (PMID 30499222, 2019). "TRPM1 was the first TRPM identified in mammals, and in some melanoma cell lines its expression level inversely correlates with their metastatic potential." (PMID 30248976, 2018). "Interestingly, loss of TRPM1 has been described as a marker of melanoma aggressiveness and tumor thickness although how this affects Ca2+ homeostasis has not been investigated, nor has the influence of TRPM1 on SOCE in invasive melanoma been determined." (PMID 27417567, 2016). "By transcriptionally up-regulating TRPM1, MITF, which is critical for both melanocyte differentiation and survival and for melanoma progression, indirectly drives the expression of miR-211." (PMID 24039954, 2013). "We confirm this strong correlation in 10 of 11 tested melanoma cell lines, which clearly supports the idea that MITF drives expression of TRPM1 and by doing so it up-regulates miR-211, an intronic passenger of this gene." (PMID 24039954, 2013). "TRPM1, the founding member of the TRPM channel subfamily was discovered in a screen looking for transcriptional regulation in melanoma." (PMID 24084011, 2013). "Among 142 upregulated genes in melanoma, many are known to be expressed specifically in melanocytes, including KIT, Melan-A, TYR, TRPM1, EDNRB, DCT, SOX10 and SILV." (PMID 21294715, 2011). "We characterized melanoma cells and conducted dimensionality reduction clustering, revealing six distinct cell subgroups: C0 TRPM1+ Melanoma cells, C1 PIR+ Melanoma cells, C2 PHLDA2+ Melanoma cells, C3 ID2+ Melanoma cells, C4 PCLAF+ Melanoma cells, and C5 CD74+ Melanoma cells." (PMID 39781353, 2025). "The founding member of the TRPM subfamily, TRPM1, was discovered in 1998 as a protein present in benign nevi, but not in malignant melanoma." (PMID 32887395, 2020). "Interestingly, TRPM1 was not directly linked to patients’ survival but to favorable pathological variables, such as Breslow’s depth and absence of ulceration, which is in line with other authors who defined TRPM1 loss as an excellent marker of melanoma aggressiveness." (PMID 33003444, 2020). "According to some studies, TRPM1 transcription regulation seems to occur via the binding of microphthalmia transcription factor (MITF), which is an essential transcription factor for the development of melanoma." (PMID 29875336, 2018). "Furthermore, melanoma cells with low MITF levels that were transfected with vectors for expression of MITF and OCT4 showed a significant decrease in TRPM1 mRNA levels compared to the control." (PMID 29044103, 2017).
melanoma (continued). "TRPM1 and TRPM3 are members of the mammalian melastatin-like transient receptor potential (TRPM) channel subfamily including eight members based on their homology to melastatin (TRPM1), a putative tumor suppressor involved in the pathophysiology of melanoma." (PMID 24084011, 2013). "Increasing expression of miR-211 but not TRPM1 reduces migration and invasion of malignant and highly invasive human melanomas characterized by low levels of melastatin and miR-211." (PMID 24204345, 2013). "The absence of TRPM1 in malign melanoma guided the authors to name the TRP channel identified melastatin." (PMID 24084011, 2013). "We found that both TRPM1 and miR-211 transcripts are expressed in pigmented but not in the non-pigmented melanoma cells." (PMID 21072171, 2010). "Although not temperature-sensitive, TRPM1 is worth mentioning, since TRPM1 mRNA CISH may distinguish between melanoma and Spitz nevi." (PMID 37240443, 2023). "TRPM1 CISH may also help distinguish Spitz nevi from melanoma; complete absence of TRPM1 mRNA was observed in 27 out of 33 (82%) of melanomas, but only 1% (1 in 95) of Spitz nevi." (PMID 37240443, 2023). "TRPM1 elevates [Ca2+]-cytosolic levels and activates Ca2+/calmodulin-dependent protein kinase IIδ (CaMKIIδ), promoting AKT activation after CaMKIIδ/AKT interaction, cell mobility, colony formation, and tumor growth in an in vivo (xenograft) melanoma cell model." (PMID 36844925, 2022). "In fact, TRPM1 mRNA is almost or totally absent in around 80% of invasive primary melanomas." (PMID 29875336, 2018). "In addition, expression of TRPM1 is a sensitive readout of MITF activity levels, and a minimal TRPM1 promoter, which has an MITF peak in melanoma cells and primary melanocytes, has activity in melanoma cells that is lost upon deletion of the MITF binding sites." (PMID 28249010, 2017). "If true, it raises the possibility that one of the ways MITF might also suppress melanoma metastasis is through its transcriptional activation of miR-211 via the TRPM1 promoter, and the consequent negative post-transcriptional effects of miR-211 on KCNMA1 mRNA." (PMID 21072171, 2010). "A recent study, however, showed that TRPM1 did not predict overall survival in patients with clinical AJCC stages I and II melanoma." (PMID 29108231, 2017).
congenital stationary night blindness (27 papers, 2010 to 2025). "We reported 4 variants in TRPM1, a gene associated with congenital stationary night blindness (CSNB), a genetically and clinically heterogeneous disease that manifests as non-progressive nyctalopia and with an electronegative full-field electroretinogram." (PMID 35457050, 2022). "ALMS1 mutations cause autosomal recessive Alström syndrome whereas TRPM1 mutations are associated with recessive congenital stationary night blindness." (PMID 34485303, 2021). "In that respect, mutations in the human TRPM1 gene lead to defects in the depolarizing light response of ON-bipolar cells and cause congenital stationary night blindness in patients." (PMID 29209045, 2017). "The closest relative of TRPM3 is TRPM1, which is expressed in retinal ON-bipolar cells, and its mutations in humans cause congenital stationary night blindness." (PMID 28829742, 2017). "Reduced expression of the transient receptor potential cation channel, subfamily M, member 1 (TRPM1) in retinal ON bipolar cells causes congenital stationary night-blindness (CSNB) in Appaloosa, Knabstrupper and other horse breeds." (PMID 27329127, 2016). "Recent studies demonstrate that mutations in the TRPM1 gene underlie the inherited retinal disease complete congenital stationary night blindness in humans and depolarizing bipolar cell dysfunction in the mouse retina, but auditory function was not assessed." (PMID 24146970, 2013). "In humans, a mutation in TRPM1 causes the complete form of congenital stationary night blindness (cCSNB), an autosomal recessive disease that is characterized by depolarizing bipolar cell (DBC) dysfunction." (PMID 24146970, 2013). "Recently, four groups including ours independently reported that mutations of human TRPM1 are associated with the complete-type of congenital stationary night blindness (cCSNB), an inherited human retinal disease." (PMID 21611200, 2011). "The TRPM1 mutation is the most common cause of congenital stationary night blindness (CSNB), which could reduce the chance to survive in the wild since vision is key for communication, localization, orientation, avoiding predators, and looking for food." (PMID 36661852, 2023). "GRM6 and TRPM1 are bipolar DEGs and their mutations could cause a recessive congenital stationary night blindness (CSNB), a condition due to abnormal photoreceptor-bipolar signaling." (PMID 31848347, 2019). "Human TRPM1 mutations are associated with congenital stationary night blindness (CSNB)." (PMID 29854741, 2018). "In addition, this and other groups have reported that human TRPM1 mutations are associated with the complete form of congenital stationary night blindness." (PMID 21611200, 2011). "The exact role of TRPM1 in ON-bipolar cells interacting with other membrane proteins, like nictalopin and glutamate receptors, is complex, but it is now known that mutations in the human TRPM1 gene lead to autosomal recessive complete congenital stationary night blindness (CSNB; OMIM: 613216)." (PMID 39457382, 2024). "We noted heterozygous variants in two genes known to cause congenital stationary night blindness (CSNB): GRM6 (c.2092 C > G: p.(L698V)) and TRPM1 (c.3958 G > A: p.(E1320K))." (PMID 33776059, 2021). "In addition, two unique variants carried by TRPM1 and CACNA1F, known to cause congenital stationary night blindness were uniquely identified in the patient." (PMID 33374679, 2020). "Its role in the retina is unknown but its expression is rather eye-specific (UniGene Hs.159241) and may represent a candidate gene for inherited retinal dystrophies, as TRPM1 was found to be involved in congenital stationary night blindness." (PMID 22174898, 2011). "Finally, TRPM1 encodes a cation channel and pathogenic variants in the gene are associated to congenital night blindness, but no inherited cancer syndrome is described." (PMID 33827643, 2021).
congenital stationary night blindness (continued). "Integrated expression and transcription regulatory network genes, such as congenital stationary night blindness (CSNB) genes GRK1, PDE6B, and TRPM1, showed cell-specific expression and transcription characteristics in either rods or bipolar cells (BCs)." (PMID 39055259, 2024).
myopia (10 papers, 2019 to 2026). "TRPM1-related myopia keeps progressing during the first decade of life, warranting regular screening and consideration of early myopia control interventions to mitigate the risk of myopia-related sight-threatening complications." (PMID 40935931, 2025). "According to our three cases of the complete type, two cases of NYX gene mutations showed high myopia and poor visual acuity, whereas one case of TRPM1 gene mutations showed high myopia but retained visual acuity." (PMID 34064005, 2021). "The complete-type patient with autosomal recessive TRPM1 gene mutation showed high myopia with relatively good BCVAs in both eyes." (PMID 34064005, 2021). "This study suggests that pathogenic variants in TRPM1 are associated with high myopia in CSNB patients, where altered signalling in ON-bipolar cells may promote axial elongation of the eye, resulting in high myopia." (PMID 41153400, 2025). "High myopia was associated with the NYX (n = 4, −8.34 ± 1.75D), RPGR (n = 3, −8.63 ± 2.69D) and TRPM1 (n = 3, −8.92 ± 2.63D) genes." (PMID 41465105, 2025). "Another longitudinal study followed 7 pediatric patients with TRPM1-associated CSNB, where 5 of the 7 patients had progressive myopia, strabismus and nystagmus." (PMID 41153400, 2025). "Our results align with previous studies, such as Hendriks and associates’ findings on CSNB patients, who demonstrated high myopia, especially in those with mutations in the CACNA1F, NYX, and TRPM1 genes." (PMID 40935931, 2025). "Igelman and associates focused on the progressive aspect of myopia among CSNB paediatric patients, analysing samples of 78 paediatric patients with CSNB, out of which 41 with CACNA1F, 22 with NYX and 15 with TRPM1 genes." (PMID 40935931, 2025). "Early-onset myopia was more common in patients with mutations of NYX, GRM6, and TRPM1 than in patients with CACNA1F mutations, further supporting the link between the mGluR6 signaling pathway and myopia." (PMID 38448886, 2024). "By age of 6 years, however, the eyes in the TRPM1 group had comparable myopia and axial length to those in the NYX group." (PMID 38448886, 2024). "The parents are nonconsanguineous Ashkenazi Jews of Lithuanian and Russian descent, with four children out of 7 exhibiting exotropia, myopia and CSNB caused by the homozygous TRPM1 exon 2–7 deletion." (PMID 31645983, 2019). "Homozygous deletion of exons 2–7 in TRPM1 is a common cause of CSNB and myopia in many Ashkenazi Jewish patients." (PMID 31645983, 2019). "We demonstrated a homozygous deletion in exons 2–7 of TRPM1 in 6 Ashkenazi Jewish families with early-onset myopia and CSNB." (PMID 31645983, 2019). "TRPM1 patients had the highest degree of myopia and longest ocular axis at age of 3 years." (PMID 38448886, 2024). "Furthermore, Patients 3–5 have myopia, nystagmus, and strabismus, which have been previously associated with CSNB due to the TRPM1 mutation." (PMID 36499293, 2022). "The CACNA1F group had relatively lower myopia and axial length than the NYX and TRPM1 groups, both at age 3 and age 6 years." (PMID 38448886, 2024). "Genes involved in the depolarization of ON bipolar cells include TRPM1, NYX, GPR179—detected in our described patient—and LRIT3, which, when damaged, similarly cause a negative ERG and are associated with high myopia." (PMID 40004769, 2025). "The Riggs and TRPM1 complete types presented mild myopia and good BCVA without strabismus and nystagmus, whereas the NYX complete and incomplete types showed mixed SE and poor BCVA with strabismus and nystagmus." (PMID 34064005, 2021).
night blindness (6 papers, 2016 to 2024). Inability to see clearly in dim light. "From ‘light-blindness’ in fruit flies (trp) to ‘night-blindness’ in humans (TRPM1), TRP channels have been identified as evolutionarily important Ca2+ sensors in the photosensitive retina." (PMID 32070426, 2020). "Such TRP channelopathies include night blindness (TRPM1), progressive familial heart block type I (TRPM4), hypomagnesemia with secondary hypocalcemia (TRPM6), and autosomal dominant polycystic kidney disease (TRPP2), to name a few." (PMID 26490951, 2016). "In addition, TRPM1 mutations (bi-allelic and deletion) can present in childhood as progressive high-myopia, involuntary eye movements (nystagmus, strabismus, or squint), and an abnormal (electronegative) full-field ERG with or without stationary or progressive night-blindness." (PMID 32070426, 2020).
prostate carcinoma (5 papers, 2012 to 2025). A carcinoma that arises from epithelial cells of the prostate gland. "Within these pleiotropic genes, MXR5 was associated with colorectal cancer; TRPM1 and UCKL1 were linked to prostate cancer, and TTN was associated with both cancer types." (PMID 41234971, 2025). "TRPM1, TRPM8, and TRPV6 are considered to be tumor suppressors and oncogenes in localized melanoma and prostate cancer, respectively." (PMID 22523714, 2012).
retinal disease (4 papers, 2011 to 2024). "Hendriks et al48 found that NYX and TRPM1 patients were in the top 3 myopic groups in a cross-sectional study in 302 patients with inherited retinal diseases." (PMID 38522615, 2024).
melanoma associated retinopathy (3 papers, 2013 to 2024). Melanoma-associated retinopathy (MAR) is a rare autoimmune condition that occurs in some people with melanoma (a type of skin cancer) and can affect the vision. "Additionally, TRPM1 is associated with melanoma-associated retinopathy, triggered by ON bipolar cells expressing TRPM1 autoantibodies." (PMID 39633507, 2024).